ENSG00000249773 (novel zinc finger protein 713 (ZNF713) and mitochondrial ribosomal protein S17 (MRPS17) protein)
Gene: Protein-coding gene on chromosome 7 (55,887,277 to 55,955,239, forward strand). Ensembl gene ENSG00000249773.
Genetic constraint (gnomAD): Loss-of-function variants: 21 observed, 26.98 expected, observed/expected ratio (o/e) 0.78, 90% interval 0.55 to 1.12. Missense variants: 231 observed, 279.18 expected, observed/expected ratio (o/e) 0.83, 90% interval 0.74 to 0.92. Synonymous variants: 96 observed, 105.02 expected, observed/expected ratio (o/e) 0.91, 90% interval 0.77 to 1.08.